CRP (C-reactive protein)
Diseases named in the same sentence as CRP in open-access papers (continued):
Sharing a sentence is not in itself a finding about the gene and the disease.
spondylitis (continued). "Further, the concentration of miR-155 was found correlated with CRP concentrations and BASDAI (Bath Ankylosing Spondylitis Disease Activity Index) and mSASSS (modified Stoke Ankylosing Spondylitis Spinal Score) values, suggesting a plausible utility for miR-155 as a marker of disease activity." (PMID 34216293, 2021). "Besides, CAR was positively correlated with erythrocyte sedimentation rate (ESR) (r = 0.704, P < 0.001), CRP (r = 0.996, P < 0.001), BASDAI (r = 0.329, P < 0.001), and Bath Ankylosing Spondylitis Functional Index (BASFI) (r = 0.330, P < 0.001)." (PMID 34234877, 2021). "To summarize the impact of TNFi on MRI inflammation assessed by SPARCC score, we performed the meta-analysis, accompanied with other assessment indicators including Ankylosing Spondylitis Disease Activity Score (ASDAS), BASDAI, BASFI, and C-reactive protein (CRP)." (PMID 33382842, 2020). "In addition to the previously observed correlation of BMP-2 levels with the Bath Ankylosing Spondylitis Indexes, we noticed a correlation with OPG and CRP markers." (PMID 33046134, 2020). "Notably, no single SNP was found to associate with sMICA levels and serum sMICA concentrations were not correlated with ESR, CRP, BASFI (Bath Ankylosing Spondylitis Functional Index) and BASDAI (Bath Ankylosing Spondylitis Disease Activity Index) (data not shown)." (PMID 34208618, 2021).
respiratory infections (100 papers, 2007 to 2025). "The association between CRP level and antibiotic prescribing closely mirrors previous findings in patients with respiratory infections in Danish PHC and aligns with results from a small prospective study in Swedish PHC." (PMID 39460385, 2025). "Future studies should expand the sample size, explore the distinct roles of CRP isoforms, and investigate additional pathways by which CRP regulates apoptosis, particularly in respiratory infections associated with MP." (PMID 39932324, 2025). "CRP is an effective diagnostic marker to differentiate viral and mixed/bacterial infection in respiratory infections." (PMID 33816347, 2021). "Previous study indicated that continuous high levels of C-reactive protein in respiratory infections increases the risk of progression to a critical disease state." (PMID 33175876, 2020). "Two other studies of patients undergoing cardiac surgery also showed that elevated preoperative CRP levels were associated with increased postoperative respiratory infection risk." (PMID 23457535, 2013). "Relevant for the current review are previous observations suggesting a reduced risk for respiratory infections with the MeD and especially a reduced risk of inflammation, with a decrease in C-reactive protein (CRP) and pro-inflammatory cytokines, such as interleukin (IL)-6 and IL-1β." (PMID 37048015, 2023). "Nevertheless, it is also thought that respiratory infections may be the underlying cause for rapid rise in CRP during months before death." (PMID 35201675, 2022). "Moreover, the PCT and CRP are significantly associated with the severity of HAdV respiratory infections in children." (PMID 33145348, 2020). "The interplay between a semi-quantitative value for CRP and MxA can help to identify patients with a clinically significant underlying immune response consistent with a suspected respiratory infection from those patients representing a microbiologically unconfirmed respiratory illness (MURI)." (PMID 26672961, 2015). "Additionally, it remains unclear whether CRP levels correlate with antibiotic prescribing in pharyngotonsillitis, although studies on respiratory infections, including acute sore throat, suggest this association." (PMID 39460385, 2025). "However, the mechanisms underlying CRP seasonal variations remain unknown, though the high CRP levels might be induced by respiratory infections in winter-spring." (PMID 26569292, 2015). "Matching the inflammatory reaction during respiratory infection or acute rejection, a significant moderate correlation was observed between %ddcfDNA and CRP levels (r=0.23, p<0.0001) over all measurements." (PMID 39944692, 2025). "For instance, a recent meta-analysis found that CRP-guided antibiotic therapy in respiratory infections reduced unnecessary antibiotic prescriptions by 22-36% without increasing the risk of treatment failure." (PMID 40693097, 2025). "Blood testing represents a pivotal diagnostic modality for differentiating respiratory infections, utilizing routinely measured parameters including complete blood count indices (e.g., leukocyte subsets, NLR) and inflammatory biomarkers such as CRP and SAA." (PMID 41308272, 2025). "C-reactive protein levels were transiently 1.5 times higher than normal (up to 7.5 mg/mL) in four children with respiratory infection symptoms; these levels then normalized to 5 mg/mL, and this level was subsequently maintained." (PMID 41300842, 2025). "It suggests that CRP tests are used in a similar manner in patients with pharyngotonsillitis as in patients with other respiratory infections." (PMID 39460385, 2025). "Future prospective multicenter cohorts should enroll diverse COPD patients with acute lower respiratory infections across severity strata, employing standardized CRP assays alongside inflammatory mediators (IL-6, TNF-α)." (PMID 40630494, 2025).
respiratory infections (continued). "Considering inflammatory states, a transient decrease in lipid subspecies abundances consisting of TAG, LPC and PE O- was found to correlate with an elevation in c-reactive protein and neutrophils during respiratory infections." (PMID 38473733, 2024). "HOTTIP levels (P < 0.001) can independently influence the development of ARDS, as well as COPD (P = 0.014), respiratory infection (P = 0.048), and higher CRP (P = 0.029)." (PMID 38238652, 2024). "CRP was significantly elevated in patients with COVID‐19 compared with healthy controls (p < .001) and non‐COVID‐19 respiratory infection (p < .05)." (PMID 35780481, 2022). "For comparison, in Sweden the level of CRP is measured in up to 50% of all consultations for respiratory infections." (PMID 36127630, 2022). "In a multivariate logistic regression, respiratory infection and CRP level were found to be predictive of 28-day mortality (2.594, 1.060–6.348, p = 0.037; 1.076, 1.032–1.123, and p = 0.001)." (PMID 35962331, 2022). "Elevated levels of CRP are a common feature of unresolved inflammation following respiratory infections." (PMID 33396578, 2020). "Other features were increased respiratory infection and inflammation (WBCs, 14.8 ± 5.2 vs. 14.7 ± 4.4 103/μl; CRP, 8.4 ± 6.8 vs. 5.1 ± 5.6 mg/dl)." (PMID 32293463, 2020). "Recently, she had an upper respiratory infection with markedly increased CRP and decreased leukocytes." (PMID 32601727, 2020). "Further investigation is needed to examine potential modifiers of the relation between RBP and CRP and AGP from other causes of inflammation such as tissue injury, intestinal parasites, respiratory infections, aflatoxin, and HIV." (PMID 28615251, 2017). "Given the role of CRP as an acute-phase reactant, elevated concentrations at day 1 likely reflect the impact of respiratory infection on the host inflammatory responses in the systemic circulation." (PMID 28328968, 2017). "We therefore reexamined the performance of CRP and chose to illustrate this in the subcohort of patients with respiratory infections." (PMID 28468981, 2017). "Four patients had a respiratory infection which was supposed to be of viral origin but three of them received oral antibiotics (doxycycline, cephalexin or co-amoxyclavulanate) and their CRP levels ranged 16–101 mg/L." (PMID 28235076, 2017). "Studies from Sweden have shown that CRP was used in 36–42 % of respiratory infections in 2005 and that is the same level we found at daytime services in our study." (PMID 26585447, 2015). "This sharp increase in CRP is a precursor to a full-blown MP respiratory infection in children." (PMID 39932324, 2025). "Indeed, infants who were breastfed for longer than six months recovered from respiratory infections after experiencing a milder infection with lower CRP levels and shorter periods of hospitalization." (PMID 35747896, 2022). "In the univariate Cox regression analysis, an inability to ambulate, respiratory infection, CRP level, albumin level and CAR were found to have statistically significant effects on the 28-day survival rate (p = 0.031, p = 0.043, p < 0.001, p = 0.013 and p < 0.001)." (PMID 35962331, 2022). "Notably, only CRP reached statistical significance in patients with COVID‐19 compared with non‐COVID‐19 respiratory infection." (PMID 35780481, 2022). "Besides, expression levels of TUG1 have been negatively correlated with respiratory infection, serum creatinine, white blood cell, C-reactive protein, APACHE II score, and SOFA score." (PMID 34956235, 2021). "Reimbursement issues, the need for quality control and impact on workflows were other factors identified in a European study affecting the adoption of apoint of care c-reactive protein test in primary care clinics to limit antibioticuse in lower respiratory infections." (PMID 32134929, 2020).
respiratory infections (continued). "It is notable that in adenovirus infection, the specificity of CRP significantly decreased at all cutoffs (p < 0.04), whereas that of the host-protein signature did not (p = 0.16) as compared to the specificity attained for all respiratory infections." (PMID 29700762, 2018). "In conclusion, in this study, the host-protein signature comprising TRAIL, IP-10, and CRP exhibited the highest diagnostic performance for distinguishing between bacterial and viral etiologies in patients with respiratory infections and fever without source." (PMID 29700762, 2018). "The diagnostic patterns between CRP and HNL were essentially identical whether all patients with respiratory infections were included or only patients with upper respiratory infections were examined." (PMID 28468981, 2017). "However, with the inclusion of the patients with likely etiology of their upper respiratory infection, only the diagnostic performance of HNL was superior, with an LR+ of 9.6 and LR− of 0.18, compared to 4.1 and 0.62 for CRP, respectively." (PMID 28468981, 2017). "Likewise, another Swedish study reported that 42% of all patients with a diagnosis of respiratory infection were examined with a CRP test." (PMID 28125965, 2017). "Other studies of children with respiratory infections that have observed increased CRP levels among cases with certain viruses detected have a similar problem of inability to rule out concurrent bacterial infections and inability to confirm viral etiology because of lack of gold standard tests." (PMID 28575375, 2017). "Twenty-nine percent of children had an elevated plasma AGP, suggestive of prolonged inflammation, while 6% had a raised CRP, possibly reflecting more acute infection, and a rate that was comparable in magnitude those of lower respiratory infection (2%) and diarrhea (4%) in the past week." (PMID 27039242, 2016). "As higher levels of Neu, NLR, WBC, and CRP are suggestive of the presence of infection, the observed seasonality could imply higher rates of minor respiratory infections in winter-spring than summer-fall." (PMID 26544180, 2015). "Because younger children easily contract respiratory infections, low grade inflammation due to subclinical respiratory conditions may influence serum CRP concentration in young children." (PMID 17827864, 2007). "Furthermore, a 2022 Cochrane systematic review examining the use of POCTs in respiratory infections demonstrated that CRP-POC testing, when used alongside clinical assessment and patient history, led to decreased antibiotic prescriptions both immediately and within 28 days of follow-up." (PMID 41471239, 2025). "However, at OOH we found the usage rate of CRP to be almost 60 % for respiratory infections." (PMID 26585447, 2015). "For children, CRP POCT, in combination with communication training, has resulted in a positive effect in reducing antibiotic prescribing for respiratory infections in general practice." (PMID 39335040, 2024). "Laboratory changes were less pronounced in respiratory infections, with a median PCT increase of 18.9% (-14.1–224.2%) and CRP increase of 114.9% (IQR 14.61–290.5%)." (PMID 35420370, 2022). "In the 36 patients included in this brief report, a diagnosis of respiratory infection was suggested by clinical history and elevated values of systemic inflammatory markers (WBC count, CRP, and PCT) at admission." (PMID 34350202, 2021). "With respect to respiratory infections, the combination of POCT of the level of C-reactive protein and clinical assessment has been shown to have a significant effect on antibiotic prescribing." (PMID 34441037, 2021). "The AUC-ROC of CRP was 0.56 (95% CI, 0.50–0.62, p = 0.04) for GPC and 0.39 (95% CI, 0.32–0.45, p < 0.01) for GNB respiratory infection." (PMID 33810263, 2021). "Of the 84 children with febrile respiratory infection due to HAdVs, 25% had increased (>15000/mm3) WBC count, and 31% had elevated (>40 mg/l) CRP levels." (PMID 33145348, 2020).
respiratory infections (continued). "Several randomized trials have assessed CRP and PCT for deciding on antibiotic prescription for respiratory infections in adults." (PMID 29059253, 2017). "Using CRP and PCT cutoffs, integrated into an overall disease management algorithm, for the management of children with respiratory infections and FWS was safe in terms of clinical outcome." (PMID 29059253, 2017). "Aim of the present study was to evaluate the suitability of Lf, CRP, LBP, and Hp as local biomarkers in respiratory infections in cattle using a well-defined animal model." (PMID 26209015, 2015). "The aim of this study is to determine if C-reactive protein (CRP) levels and white blood cells (WBC) count are considerable markers to help rapid diagnosis and prediction of antibiotic need for lower respiratory infections in emergency departments." (PMID 23497669, 2013). "One notable randomized trial, conducted in Nigeria, demonstrated that CRP testing combined with pharmacist training reduced non-prescription antibiotic dispensing for respiratory infections, although such context-specific evidence remains limited." (PMID 41463788, 2025). "Some commonly used indicators of inflammation such as C-reactive protein, erythrocyte sedimentation rate, leukocyte and neutrophil percentages are also elevated in patients with CIP, so CIP cannot be well distinguished from respiratory infections." (PMID 36869304, 2023). "Collectively, patients bearing COVID-19 infection exhibited significantly higher levels of serum CRP (>100mg/ml) compared to either the healthy ones or non-COVID patients with respiratory infection." (PMID 38077346, 2023). "The comparison of baseline characteristics of patients according to in-hospital mortality revealed that the patients who died were more likely to have suffered from a respiratory infection, had a lower eGFR using the CKD-EPI formula and had a higher value of CRP compared to surviving patients." (PMID 34649512, 2021). "21/36 of respondents (58.3%) did not use any POCT for managing respiratory infections, 7 (19.4%) used a CRP test and five (13.9%) a ‘Strep A’ test." (PMID 30067760, 2018). "In this study, we compared the performance of individual and combined biomarkers and prediction rules to a recently developed signature comprising three host-proteins—TRAIL, IP-10, and CRP—in patients with respiratory infections and fever without source." (PMID 29700762, 2018). "However, C-reactive protein levels were significantly higher in children with recurrent respiratory infections (6.8 mg/L) compared to those without (3.1 mg/L), with a p-value of <0.001." (PMID 38892528, 2024). "ESR and CRP are non-specific inflammatory markers; CRP may be used to decide on antibiotic use, e.g., for respiratory infections." (PMID 38730361, 2024). "Some GPs felt that the CRP point-of-care test might be only useful for respiratory infections and not for UTIs." (PMID 35879106, 2022). "Seropositive individuals had higher levels of CRP, TNF, and IL-6 in circulation 1–3 months post-symptom onset; but in samples from individuals 6–9 months post-symptom onset, levels were equivalent to those individuals who were seronegative and were recovered from other respiratory infections." (PMID 34835045, 2021). "Beside LBP, the suitability of Hp and Lf as local biomarkers of respiratory infections in cattle and their role in the local response to pathogens is worth further investigation, while CRP does not seem to play a role in local defense mechanisms of the bovine lung." (PMID 26209015, 2015). "Such a small reduction in prescription rate could be achieved on clinical grounds alone: in our study 43% (392/920) of patients in the e-POCT arm with cough did not meet clinical criteria for CRP testing and were categorized as having an upper respiratory infection." (PMID 29059253, 2017).